MME (membrane metalloendopeptidase)
Description:
Thermolysin-like specificity, but is almost confined on acting on polypeptides of up to 30 amino acids. Biologically important in the destruction of opioid peptides such as Met- and Leu-enkephalins by cleavage of a Gly-Phe bond. Catalyzes cleavage of bradykinin, substance P and neurotensin peptides. Able to cleave angiotensin-1, angiotensin-2 and angiotensin 1-9. Involved in the degradation of atrial natriuretic factor (ANF) and brain natriuretic factor (BNP(1-32)). Displays UV-inducible elastase activity toward skin preelastic and elastic fibers.
Synonyms: CALLA; NEP; SFE; CD10; CMT2T; SCA43
Tractability: Small molecule: an approved drug acts on it; a structure with a bound ligand is known; a high-quality ligand is known; it has a high-quality binding pocket; it belongs to a druggable protein family. Antibody: UniProt places it where antibodies can reach, with high confidence; its Gene Ontology location is reachable by antibodies, with high confidence; UniProt predicts a signal peptide or a membrane-spanning region. PROTAC: its protein half-life has been measured; a small molecule that binds it is known.
Target class: Metallo protease; Enzyme; Metallo protease MAE clan; Metallo protease M13 family; Protease
Safety:
Unwanted effects reported when the protein is acted on. In parentheses: how it was acted on, where the effect was seen, and who reports it.
cough (source: ClinPGx)
Gene: Protein-coding gene on chromosome 3 (155,024,124 to 155,183,803, forward strand). Ensembl gene ENSG00000196549.
Subcellular location: Cell membrane
Subcellular location (Human Protein Atlas): Basal body; Centrosome; Plasma membrane; Cytosol
Pathways (Reactome):
Developmental Biology: Developmental Lineage of Mammary Gland Myoepithelial Cells
Immune System: Neutrophil degranulation
Metabolism of proteins: Metabolism of Angiotensinogen to Angiotensins
Muscle contraction: Physiological factors
Gene Ontology:
Molecular function: cardiolipin binding; endopeptidase activity; exopeptidase activity; metalloendopeptidase activity; phosphatidylserine binding; protein binding; protein homodimerization activity; zinc ion binding; peptide binding; metallocarboxypeptidase activity; metallopeptidase activity; oligopeptidase activity; peptidase activity
Biological process: amyloid-beta clearance; amyloid-beta clearance by cellular catabolic process; bradykinin catabolic process; cellular response to cytokine stimulus; cellular response to UV-A; cellular response to UV-B; creatinine metabolic process; hormone catabolic process; kidney development; learning or memory; neuropeptide processing; positive regulation of neurogenesis; proteolysis; replicative senescence; substance P catabolic process; amyloid-beta metabolic process; peptide metabolic process; protein processing; sensory perception of pain; angiotensin maturation; lung development; placenta development; positive regulation of long-term synaptic potentiation; protein catabolic process; response to estrogen
Cellular component: axon; brush border; cytoplasm; cytoplasmic vesicle; early endosome; extracellular exosome; focal adhesion; membrane raft; neuronal cell body; plasma membrane; presynapse; trans-Golgi network; cell surface; dendrite; membrane; neuron projection terminus; secretory granule membrane; synapse; synaptic vesicle; extracellular region
Genetic constraint (gnomAD): Loss-of-function variants: 59 observed, 78.68 expected, observed/expected ratio (o/e) 0.75, 90% interval 0.61 to 0.93. The upper end of that interval is the gene's LOEUF score, 0.93, which puts it in group 3 of 6, group 1 being the genes least tolerant of losing a copy. Missense variants: 653 observed, 746.01 expected, observed/expected ratio (o/e) 0.88, 90% interval 0.82 to 0.93. Synonymous variants: 232 observed, 249.27 expected, observed/expected ratio (o/e) 0.93, 90% interval 0.83 to 1.04.
Gene-disease validity (ClinGen):
ClinGen rates the evidence that MME causes each of these diseases.
Charcot-Marie-Tooth disease axonal type 2T (autosomal recessive): Definitive. A Charcot-Marie-Tooth disease type 2 that has material basis in homozygous or compound heterozygous mutation in the MME gene on chromosome 3q25.
Homologues: Orthologues: chimpanzee MME (99% identical), macaque MME (99% identical), rat Mme (94% identical), mouse Mme (94% identical), rabbit MME (94% identical), pig MME (93% identical), dog MME (93% identical), guinea pig MME (89% identical), tropical clawed frog mme (51% identical), Drosophila melanogaster Nep4 (38% identical), Drosophila melanogaster Nep3 (37% identical), Caenorhabditis elegans nep-1 (32% identical), and 20 more. Paralogues in human: MMEL1 (53% identical), ECE1 (38% identical), PHEX (35% identical), ECEL1 (35% identical), ECE2 (34% identical), KEL (22% identical).
Diseases named in the same sentence as MME in open-access papers:
MME is named in the same sentence as 396 diseases in open-access papers, as found by Europe PMC text mining. Sharing a sentence is not in itself a finding about the gene and the disease. The quoted sentences say what the papers report.
lymphoma (105 papers, 2009 to 2026). A malignant (clonal) proliferation of B- lymphocytes or T- lymphocytes which involves the lymph nodes, bone marrow and/or extranodal sites. "In addition, new analysis predicted lymphoma subtypes using cell-of-origin markers that hematopathologists use in the clinical routine, including CD3, CD5, CD19, CD79A, MS4A1 (CD20), MME (CD10), BCL6, IRF4 (MUM-1), BCL2, SOX11, MNDA, and FCRL4 (IRTA1)." (PMID 38745770, 2024). "The ΔEBNA2 + Myc lymphomas also express the GC marker CD10 (MME), while ΔEBNA2 lymphomas have higher expression of CD30 (a B cell activation marker), BLIMP1 (PRDM1, a marker for plasma cell differentiation) and BZLF1 (a lytic EBV protein) in comparison to ΔEBNA2 + Myc lymphomas." (PMID 38620028, 2024).
renal cell carcinoma (65 papers, 2009 to 2026). "MME (CD10/CALLA), a matrix metalloendopeptidase, is a well known marker of B-cell acute lymphoblastic leukemia and has also been linked to renal cell carcinoma." (PMID 25969993, 2015).
breast carcinoma (58 papers, 2006 to 2025). "As MME was significantly downregulated in tumor tissues and is involved in the PI3K/Akt pathway, we suggest that MME may act as a tumor suppressor in breast cancer by regulating the PI3K/Akt signaling pathway, especially its downstream FoxO signaling pathway." (PMID 37585411, 2023). "A recent study further supports a potential role of MMP2 in breast-to-brain metastasis, as it was found to belong to 5-gene expression signature (together with CXCL12, MMP11, VCAM1, MME) discriminating between primary breast cancer and breast cancer brain metastases." (PMID 29312881, 2017). "There is a number of scientific research for each of the top 10 mRNA genes, well-documenting their significance and association with cancerogenesis: ADAMTS5, TMEM220, ARHGAP20, MICU3; or precisely with breast cancer: COL10A1, MMP11, CAVIN2 (formerly known as SDPR), PLPP3, MME, and CD300LG." (PMID 40724805, 2025).
leukemia (50 papers, 2000 to 2025). A malignant (clonal) hematologic disorder, involving hematopoietic stem cells and characterized by the presence of primitive or atypical myeloid or lymphoid cells in the bone marrow and the blood. "Originally identified in leukemia as a tumor-specific antigen, CD10 (encoded by the MME gene) is associated with multiple cellular functions in normal and pathologic contexts." (PMID 37707389, 2023).
acute lymphoblastic leukemia (46 papers, 2002 to 2025). Leukemia with an acute onset, characterized by the presence of lymphoblasts in the bone marrow and the peripheral blood. "The protein encoded by the MME gene is a type II transmembrane glycoprotein and a common acute lymphocytic leukemia antigen." (PMID 38674435, 2024). "The CD10 that we examined in this study has various alternative names, including membrane metalloendopeptidase, common acute lymphocytic leukemia antigen, neprilysin, neutral endopeptidase, enkephalinase, and atriopeptidase [NCBI, OMIM]." (PMID 34360996, 2021). "The neprilysin protein (the MME gene product) is known primarily for its increased expression in one of the pre-B phenotype of acute lymphocytic leukemia, thanks to which it owes its second name, common acute lymphoblastic leukemia antigen (CALLA)." (PMID 32366041, 2020). "MME, is a proliferation blocker, can cleave signal peptides at the cell surface to affect cell proliferation and differentiation, and acts as an acute lymphocytic leukemia antigen." (PMID 28423735, 2017). "MME is a type II transmembrane glycoprotein and a common acute lymphocytic leukemia antigen." (PMID 30761252, 2019).
melanoma (33 papers, 2008 to 2026). A malignant, usually aggressive tumor composed of atypical, neoplastic melanocytes. "Genes such as KRT14, GJA1, S100A7, S100A9, and EHF were higher in most melanomas while genes such as CITED-1, GDF15, QPRT, OCA2, c-MET and MME were more highly expressed in NHEM." (PMID 18442402, 2008).
prostate carcinoma (28 papers, 2005 to 2025). A carcinoma that arises from epithelial cells of the prostate gland. "MME has been implicated in prostate cancer and though the data are conflicting on whether this gene promotes or protects against the progression, our data suggest a role for this gene in prostate cancer progression to androgen-independence." (PMID 15790403, 2005). "Membrane metalloendopeptidase (MME) is responsible for the catalytic inactivation of neuropeptide substrates, and is downregulated in nearly 50% of prostate cancers." (PMID 32205838, 2020). "MME and MTHFD1 are a pair of proteins that interact in prostate cancer cells; however, the complex structure of these proteins has not been determined." (PMID 29745830, 2018).
COVID-19 (27 papers, 2020 to 2025). A disease caused by infection with severe acute respiratory syndrome coronavirus 2. "Key proteomic features of the COVID-19 severity model also included two components of the RAS (ACE2 and MME), a complex hormonal system that regulates blood pressure and fluid homeostasis as well as pulmonary inflammation." (PMID 35839768, 2022). "Sorted cells also included immature neutrophils characterized by low expression of membrane metalloendopeptidase (MME)/CD10, a neutrophil subset that has been described to be especially prominent in COVID-19." (PMID 34403366, 2021).
colorectal cancer (23 papers, 2004 to 2025). A primary or metastatic malignant neoplasm that affects the colon or rectum. "For example, MME is overexpressed in pancreatic endocrine tumors and colorectal carcinoma but decreased in lung and ovarian cancer, suggesting cell type-specific effects of MME." (PMID 37585411, 2023). "Membrane Metalloendopeptidase (MME) is the prototype of the membrane bound zinc-dependent endopeptidase family, and it is also overexpressed in numerous malignancies, including colorectal carcinoma, pancreatic endocrine tumors, and metastatic melanomas." (PMID 35360859, 2022).
lung carcinoma (17 papers, 2014 to 2025). "The study shows that gene expression profiles in human hypoxic lung cancer tissue overlap with hypoxia-signatures from cancer cell lines, however, MME was identified as a novel hypoxia-induced gene in lung cancer." (PMID 24460801, 2014). "MME is expressed in a variety of non-malignant and malignant tissues including lung cancer." (PMID 24460801, 2014).
Alzheimer disease (14 papers, 2009 to 2025). A progressive, neurodegenerative disease characterized by loss of function and death of nerve cells in several areas of the brain leading to loss of cognitive function such as memory and language. "For instance, polymorphisms in the membrane metalloendopeptidase (MME) gene encoding neprilysin have been associated with Alzheimer’s disease and could be related to the risk of dementia with sacubitril/valsartan." (PMID 39227418, 2024). "Intriguingly, membrane metallo-endopeptidase (MME), which is considered one of the important β-amyloid (Aβ)-degrading enzymes related to prevention of Alzheimer’s disease (AD) pathology, was identified with increased abundance in all H2O2 treatment groups." (PMID 37092453, 2023). "In our previous study, we developed a liquid natural ECM biomaterial enriched with insulin-degrading enzyme (IDE) and membrane metalloendopeptidase (MME) to reduce amyloid-beta (Aβ) peptide accumulation and Tau phosphorylation in Alzheimer’s disease cell models." (PMID 34938180, 2021). "In CN samples, interestingly, among the most significant pathways enriched with significant CpGs is the KEGG pathway “Alzheimer’s disease”, which was curated based on recent AD literature and included genes that confer AD risks, such as APOE, PSENEN, MAPT, CALM3, MME, and others." (PMID 37038196, 2023).
lymph node metastasis (14 papers, 2007 to 2024). "A high level of MME (CD10) mRNA expression was associated with minimal extrathyroidal extension (p < 0.001), pathologic T stage (p = 0.006), lymph node metastasis (p < 0.001), and advanced cancer stage (p = 0.007)." (PMID 32486143, 2020).
Sepsis (14 papers, 2020 to 2025). Sepsis is defined as life-threatening organ dysfunction caused by a dysregulated host response to infection. "Still, the exact role of MME in sepsis remains to be determined." (PMID 34836493, 2021). "In this study, as a significantly upregulated gene, MME (membrane metalloendopeptidase) might play an important role in the prognosis of septic shock through the renin-angiotensin system pathway, which is activated to increase the arterial blood pressure in sepsis." (PMID 34836493, 2021). "Thus, the DE genes identified in this study, such as OLFM4, MME, CXCR2,CEACAM8, and ELANE, probably take part in pediatric sepsis development by regulationof neutrophil function." (PMID 33503200, 2021).
invasive breast carcinoma (13 papers, 2010 to 2025). A carcinoma that infiltrates the breast parenchyma. "Interestingly, only 4 reference sequences were significantly induced in the ‘1986’ clone, among these MME (membrane metallo-endopeptidase, or neprilysin and CD10, as it is alternatively termed), which is linked to higher tumor grade and poor prognosis upon expression in invasive breast carcinoma." (PMID 28402269, 2017).
hepatocellular carcinoma (12 papers, 2009 to 2025). A malignant tumor that arises from hepatocytes. "NR1I2, ESR1, ALPL, MME, IGF1, NR3C2 and PTGS2 were differentially low expressed in hepatocellular carcinoma tissues." (PMID 38842135, 2024). "Key markers, such as PTPRC, CD3E, CD4, CD79A, and CD3G in immune cells, EPCAM and KRT19 in epithelial cells, and MME and PECAM1 in stromal cells, were identified, providing crucial insights into hepatocellular carcinoma progression and immune response mechanisms." (PMID 39388011, 2024).
breast tumors (10 papers, 2011 to 2023). "MME expression is decreased in breast tumor tissues and was identified as a diagnostic biomarker for BRCA with high accuracy." (PMID 37585411, 2023). "To further examine the role of MME in BRCA progression, we compared the MME expression level between primary breast tumor samples and bone metastasis samples (GSE146661) and lung or brain metastasis samples (GSE191230) with the Wilcoxon rank sum test." (PMID 37585411, 2023). "CDK11A, MME and SEPT6 were also found to altered in 6.2%, 4.5%, and 3.7%, respectively, in a panel of 1062 breast tumours from the Cancer Genome Atlas project, either through mutation, amplification, deletion or altered gene expression." (PMID 25969993, 2015).
Metastatic tumors (9 papers, 2013 to 2025). "Thus, it is reasonable that the low expression of HSP90AB1 and MME in metastatic but not primary tumor samples and the low RPS6KB1 expression in primary but not metastatic tumor samples are correlated with prolonged survival." (PMID 38578805, 2024).
colon carcinoma (7 papers, 2010 to 2024). "GGH, CACNG4, MME, SLC30A2, CKMT2, SYN3, and SLC22A31 were identified as differentially expressed both in glycolytic-cholesterogenic subgroups as well as between colon cancers and healthy samples, and were involved in glycolysis‒cholesterol synthesis." (PMID 36569910, 2022). "We found significant differences in invasiveness between these two populations in cocultures with primary fibroblasts derived from colon cancer tissues, especially in cocultures with fibroblasts positive for CD10, a membrane metalloendopeptidase." (PMID 20711432, 2010).
invasive carcinoma (7 papers, 2009 to 2024). A carcinoma that is not confined to the epithelium, and has spread to the surrounding stroma. "Because the transition from in situ to invasive carcinoma is associated with the loss of myoepithelial layer, it is conceivable that the progressive underexpression of MME we observed in ADHs and DCISs represents a very early event in the process of malignant transformation." (PMID 25962646, 2015).
Obesity (7 papers, 2009 to 2025). Accumulation of substantial excess body fat. "We found that MORC3, NUP62, CGAS, ABI3, and RPA2 were highly expressed in lean individuals, where as LMNA, ID2, CDKN1A, TENT4B, MME, and MYC were upregulated in the PBMCs of individuals with obesity." (PMID 40847086, 2025).
urothelial carcinoma of the bladder (7 papers, 2009 to 2025). "Several studies shown that MME downregulation is strongly associated with several cancer types, including breast, colon, bladder urothelial carcinoma, and colorectal." (PMID 40014586, 2025).
lung adenocarcinoma (6 papers, 2014 to 2024). A carcinoma that arises from the lung and is characterized by the presence of malignant glandular epithelial cells. "We were able to show that MME expression is a highly significant, independent adverse prognostic factor in surgically treated lung adenocarcinoma patients in multivariate analysis involving tumor stage and MME status." (PMID 24460801, 2014).
angioedema (5 papers, 2019 to 2024). Swelling involving the deep dermis, subcutaneous, or submucosal tissues, representing localized edema. "Studies have shown that the rs989692 variant in the MME gene, which codes for NEP, was found to be significantly associated with ACEi angioedema." (PMID 34449608, 2021). "Deleterious variations in genes responsible for the control of BK release, as SERPING1, or its metabolization, as CPN, CPM, angiotensin-converting enzyme (ACE), and neprilysin (MME), are able to increase the amount of BK released or its half-life, leading to or intensifying angioedema episodes." (PMID 30847342, 2019). "In the candidate gene analysis, ETV6, BDKRB2, MME, and PRKCQ were nominally associated with angioedema (p < 0.05), but did not pass Bonferroni correction for multiple testing (p < 2.89 × 10−5)." (PMID 32080354, 2020). "ETV6, BDKRB2, MME, and PRKCQ were nominally associated with angioedema (p < 0.05), but none of the candidate genes was significantly associated after correction with multiple testing (p < 2.89 × 10−5)." (PMID 32080354, 2020).
autoimmune disease (5 papers, 2011 to 2025). A disorder resulting from loss of function or tissue destruction of an organ or multiple organs, arising from humoral or cellular immune responses of the individual to their own tissue constituents. "Membrane metalloendopeptidase, also known as neprilysin, is involved in various physiological and pathological processes, including cancer and autoimmune diseases." (PMID 39717551, 2024).
Hypertension (5 papers, 2017 to 2023). The presence of chronic increased pressure in the systemic arterial system. "In 2018, the GWAS catalog found seven candidate genes with an established pathophysiological role in hypertension, namely ACE1, ACE2, ADRB1, ADRB2, MME, CACNA2D2, and UMOD." (PMID 36902588, 2023).
infiltrating ductal carcinoma (5 papers, 2009 to 2025). "In BRCA, MME expression was significantly decreased in tumor tissues, especially in luminal B and infiltrating ductal carcinoma subtypes." (PMID 37585411, 2023). "Moreover, downregulation of MME markedly correlated with the BRCA subtypes LumB and infiltrating ductal carcinoma." (PMID 37585411, 2023).